IL9 (interleukin 9)
Diseases named in the same sentence as IL9 in open-access papers (continued):
Sharing a sentence is not in itself a finding about the gene and the disease.
psoriasis (continued). "Eosinophils are involved in type II immune response, which is related to T helper 2 cells and various interleukins (including IL-4, IL-5, IL-9, IL-13, IL-31, and IL-33, among others), differing from the IL-17/23 axis of psoriasis." (PMID 36865550, 2023). "In psoriasis, IL-9 in induced Th17-dependent psoriasis-like skin inflammation and angiogenesis was reported." (PMID 37398641, 2023). "With these findings, IL-9–positive cells infiltrated the dermis of the patients’ skin with atopic dermatitis and psoriasis, although they were insignificant." (PMID 37398641, 2023). "CA induction of IFN-γ was also higher in guttate psoriasis, whereas IL-9 induction was slightly increased in plaque psoriasis, but not significantly differently." (PMID 33546306, 2021). "Although preferred C. albicans induction of IL-9 on CLA+ T cells has already been shown in healthy donors, we observed significantly increased CA-induced IL-9 response in psoriasis patients compared to controls." (PMID 33546306, 2021). "IL-9 has been observed to induce TH17-dependent psoriasis-like skin inflammation and angiogenesis in K5." (PMID 31035677, 2019). "PUVA reduces levels of IL-9 and IL-17 in both the TGFβ transgenic and imiquimod psoriasis mouse model." (PMID 30250844, 2018). "In summary, the observations made to date suggest that circulating CLA+ T cells in psoriasis patients produce increased amounts of IL-17A, IL-17F, and IL-9, in comparison to healthy controls, when activated by S. pyogenes." (PMID 30013558, 2018). "In this context, our research with PUVA has led us to realize the potential role of IL-9 in psoriasis and CTCL." (PMID 30250844, 2018). "Our data using the K5.hTGF-β1 mice also suggest that psoriasis-like inflammation can be ameliorated by anti-IL-9 treatment." (PMID 23335955, 2013). "To gain further insight of IL-9’s role in psoriasis, we examined the functional role of this cytokine by giving intradermal injection of IL-9 into the back skin of WT mice." (PMID 23335955, 2013). "We found that injecting anti-IL-9 antibody into K5.hTGF-β1 transgenic mice not only diminished the psoriasis-like morphological changes, including cellular infiltration and neo-vascularization of the skin, but also reduced expression of IL-17A." (PMID 23335955, 2013). "Our findings now indicate a link between IL-9, a Th2 and Th9 cytokine, and Th17 pathway in psoriasis." (PMID 23335955, 2013). "More support for the role of IL-9 in psoriasis comes from our findings in K5.hTGF-β1 transgenic mice." (PMID 23335955, 2013). "In K5.hTGF-β1 transgenic mice, exhibiting a psoriasis-like phenotype, we found increased IL-9R and IL-9 expression in the skin and intradermal IL-9 injection induced Th17-related inflammation." (PMID 23335955, 2013). "To tease out the role of IL-9 in human psoriasis, we first analyzed and compared IL-9 receptor (IL-9R) expression by immunohistochemistry." (PMID 23335955, 2013). "To address the potential role of IL-9 in psoriasis we utilized both K5.hTGF-β1 transgenic mice, which exhibit a phenotype similar to human psoriasis, and wild type (WT) mice." (PMID 23335955, 2013). "Similarly, K5.hTGF-β1 transgenic (psoriasis-prone) mice exhibited a higher expression of IL-9 and IL-9R in the skin compared to control mice." (PMID 40771819, 2025). "IL-9, a cytokine synthesized by diverse immune cells, like T lymphocytes, B lymphocytes, mast cells, and macrophages, exhibits elevated expression levels in the skin tissue of psoriasis patients." (PMID 40303401, 2025). "Serum IL-9 levels were elevated in patients with psoriasis compared to those in healthy controls and were negatively correlated with disease onset age and Nail Psoriasis Severity Index." (PMID 40771819, 2025). "Interestingly, levels of CA-induced IL-9 by CLA+T/EPI cocultures were significantly higher in psoriasis than in healthy individuals." (PMID 33546306, 2021).
psoriasis (continued). "Moreover, in guttate psoriasis, the peak in IL-9 production was found on patients having the highest ASO levels indicating higher exposure to S. pyogenes." (PMID 34778294, 2021). "The involvement of IL-9 in human autoimmunity has been studied in psoriasis, where it was shown that IL-9 receptor (IL-9R) is increased in lesioned compared to healthy skin, and in lupus erythematous, where IL-9 was reported to be highly expressed in the serum." (PMID 32375811, 2020). "In a psoriasis mouse-model, IL-9 induced Th17-related inflammatory mediators." (PMID 28323859, 2017). "Injecting anti-IL-9 antibody into K5.hTGF-β1 transgenic mice not only diminished inflammation (including skin infiltration by T cells, monocytes/macrophages, and mast cells) and angiogenesis but also delayed the psoriasis-like skin phenotype." (PMID 23335955, 2013). "Our findings indicate a link between IL-9, a Th2 and Th9 cytokine, and Th17 pathway in psoriasis." (PMID 23335955, 2013). "In addition, we studied IL-9R expression in psoriatic skin lesions and on CD4+ T cells and the effect of IL-9 on IL-17A production in cultured human peripheral blood mononuclear cells or CD4+ T cells from psoriasis patients." (PMID 23335955, 2013). "Additional studies have indicated that IL-9 also plays a crucial role in guttate psoriasis by upregulating IL-17A through its impact on cutaneous lymphocyte-associated antigen (CLA)+ T cell viability, thereby promoting inflammatory responses in guttate psoriasis." (PMID 40303401, 2025). "Furthermore, IL-9 injection enhanced the Th17 pathway in the psoriasis mice model." (PMID 37398641, 2023). "For example, inhibition of IL-9 could be explored in the context of psoriasis." (PMID 29963046, 2018). "There is a strong connection between immune cells and psoriasis, specifically CD4 + T cells which create IL-9 and γά T cells which produce IL-17." (PMID 40690118, 2025). "The Multi-Analyte Flow Assay test showed that IMQ-induced psoriasis in mice had a notable effect on reducing IFN-γ, TNF-α, IL-9, IL-17F, IL-22, and IL-17A psoriasis-related inflammatory cytokines in the APLNs, Cal/Bms, and FA groups." (PMID 39534602, 2024). "Plaque and guttate psoriasis patients showed significant CLA+ T cells-dependent CA-mediated induction of IL-17F, IL17A, and IL-9 compared to unstimulated CLA+T/EPI and CA-stimulated CLA−T/EPI cocultures." (PMID 33546306, 2021). "Like in the case of S. pyogenes, CLA+ T cells, together with autologous epidermal cells, preferentially respond to C. albicans extract by inducing IL-9, IL-17A, and IFN-γ production in psoriasis." (PMID 30013558, 2018). "Indeed, the finding that IL-9 has a pathogenic role in psoriasis is coherent with our previous observation in K5.hTGF-β1 transgenic mice, in which the therapeutic response of the psoriasiform skin to PUVA treatment correlated well with the downregulation of IL-9 in the serum." (PMID 23335955, 2013). "The pro-inflammatory cytokine IL-9 secretes IFN-γ, TNF-α, IL-17, and IL-13 in psoriasis." (PMID 40690118, 2025). "For IL-9 and IL-17 a significant decline of the serum levels has been shown after 3 months of systemic MTX therapy in patients with psoriasis and furthermore IL-9 serum levels were decreased after treatment with glucocorticoids in patients with systemic lupus erythematosus." (PMID 33995403, 2021). "Likewise, previous data from our group described the increased induction of IL-9, IL-17A and IFN-γ by CLA+CD4+ T cells after C. albicans activation in four psoriasis patients compared to healthy individuals." (PMID 33546306, 2021). "Expressions of IL-9 and IL-9R are markedly increased in psoriatic skin lesions, and IL-9 stimulates the production of IL-17A by CD4+ T cells isolated from patients with psoriasis." (PMID 32210952, 2020).
psoriasis (continued). "Here, we explore potential new mechanisms of psoriasis development including the influence of HLA-Cw6 on S. pyogenes CLA+ T cell activation in guttate psoriasis, the relevance of IL-9 on microbe induced IL-17 response in guttate and plaque psoriasis, and novel effector functions of Candida albicans." (PMID 30013558, 2018). "Moreover, IL-9 significantly enhanced IL-17A production by cultured human peripheral blood mononuclear cells or CD4+ T cells, especially in psoriasis patients." (PMID 23335955, 2013). "In addition, we observed that ex vivo IL-9 stimulated the production of IL-17 by peripheral blood mononuclear cells or CD4+ T cells, especially in cells isolated from individuals with psoriasis." (PMID 23335955, 2013). "Notably, IL-9-induced secretion of IL-17A and increase in IL-17A+CD4+ T cell numbers was greater for psoriasis patients than for normal healthy controls." (PMID 23335955, 2013). "We have demonstrated how S. pyogenes preferentially induces IL-9 production during the coculture of autologous CLA+ T cells and epidermal cells in psoriasis but not in healthy controls." (PMID 30013558, 2018). "In addition, ELISPOT assays using cells from individuals with psoriasis showed that IL-9 had no ex vivo effects on numbers of IFN- γ secreting CD4+ T cells, suggesting that IL-9 makes no contribution on the Th1 component of the disease." (PMID 23335955, 2013). "Interestingly, IL-9 partially enhanced SE-induced IL-17A, but not IFN-γ, secretion by CLA+ T cells, as well as it promoted the survival of the skin-homing T cell subset in psoriasis." (PMID 34778294, 2021).
parasitic infections (29 papers, 2014 to 2025). "IL-9 is a pleiotropic cytokine and was primarily studied in the context of Th2-associated immuno-pathological conditions such as parasitic infections." (PMID 34451389, 2021). "Subsequent studies implicated a protective role for IL-9 in TH2-driven responses during murine parasitic infections, with IL-9 levels in mesenteric lymph nodes correlating with expansion of TH2 cell populations and a requirement of IL-9 for CSR to the “type-2” antibody isotypes IgG1 and IgE." (PMID 24586147, 2014). "This reduced parasite infection was abrogated when the cells were preincubated with 9CI, a neutralizing antibody against IL-9." (PMID 34722343, 2021). "The key cytokines of the Th2 immune response, IL-4, IL-5, IL-9 and IL-13, are essential in providing immunity against extracellular parasitic infections." (PMID 34451389, 2021). "The Th9 cells are a new subtype of a subset of CD4+ T cells producing the cytokine IL-9 and play important roles in promoting effective immunity against tumor and parasites infection in mice." (PMID 32243446, 2020). "Recently, new subset of CD4+T named as T helper 9 cells that express the prototypical interleukin-9 (IL-9) cytokine have been recognized in human and mice models during different parasitic infections." (PMID 32243446, 2020). "IL-9 plays a role in various parasite infections, and the role of IL-9 in protection against T. gondii merits further investigation." (PMID 30906227, 2019). "IL-9 was found to induce the expression of Mcpt1 and Mcpt2, which was often found during parasite infections and oral allergen-induced anaphylaxis." (PMID 31905768, 2019). "Interleukin-9 (IL-9) was found to play critical roles in intestinal mast cell accumulation induced in various pathological conditions, such as parasite infection and oral allergen-induced anaphylaxis." (PMID 31905768, 2019). "It has been reported that IL-9 functions in anti-inflammatory immune responses related to parasitic infection and allergic reactions." (PMID 28935867, 2017). "IL-9/Th9 responses are recently found to be important for innate and adaptive immunity particularly in parasitic infections." (PMID 25646821, 2015). "In support, IL-9 has been shown to precede and regulate TH2-associated cytokine responses in certain parasitic infections." (PMID 24586147, 2014). "For example, IL-9 has been shown to contribute to controlling Trypanosoma cruzi infections in Chagas disease’s immunopathology by neutralising the inflammatory response and increased fibrosis while limiting parasitemia." (PMID 37569646, 2023). "The immunobiological functions of IL-9 are dual in nature, as it can both promote the development of certain diseases such as hypersensitivity reactions and inhibit the progression of others such as parasitic infections." (PMID 38362587, 2023). "Since IL-9 production was demonstrated to be higher during the chronic phase of T. cruzi model infection, we investigated the role of this cytokine in the immunopathological response to parasite infection." (PMID 34722343, 2021). "IL-9 is known to be very important regulator of MMC expansion during parasite infection." (PMID 26114959, 2015). "IL-9 is involved in parasitic infections, allergy, and inflammatory processes." (PMID 25646821, 2015). "IL-9 produced by TH9 cells during the early stage of intestinal parasite infection is therefore most likely the key cytokine in regulating the expansion of MMCs seen at approximately a week after parasite infection." (PMID 26114959, 2015). "Additionally Th2/Th9 cytokine IL-9, released early during parasitic infections and important for murine worm expulsion is also secreted by MC activated synergistically with LPS, although the importance of MC-derived IL-9 in the intestine has not been proven definitively." (PMID 35967445, 2022).
parasitic infections (continued). "At 8 d PI in baso IL-4/IL-13 (−) mice, FITC-dextran levels were positively correlated with parasitemia, plasma IL-1α, IFN-γ and IL-9, while bacterial 16S copies were positively correlated with plasma IFN-γ and IL-12p40." (PMID 38780542, 2024).
Autoimmunity (28 papers, 2013 to 2025). The occurrence of an immune reaction against the organism's own cells or tissues. "Within the skin, the finding of increased dermal expression of transcripts encoding the immunomodulatory proteins IL-9 and calprotectin in patients with skin-limited IgAV points to the fine balance between immune activation and dampening in autoimmunity." (PMID 37036681, 2023). "In fact, IL-9 has been associated with autoimmunity in EAE models and in the pathogenic induction of mast cells, which may influence BBB permeability and neurodegeneration in MS." (PMID 35805128, 2022). "IL-9 contributes to inflammatory reactions in the skin, intestine and lungs, as well as cancer and autoimmunity." (PMID 41030439, 2025). "IL-9 is a pleiotropic cytokine produced by Th2 cells, ILC2s, mast cells, and basophils, playing a significant role in type 2 immunity, autoimmunity, and the immune response to tumors." (PMID 40165959, 2025). "Collectively, these findings underscore dual roles for IL-9 in autoimmunity, where it promotes pathology through Th9, Th17 or B cells, while protecting against disease through Tregs and dendritic cells." (PMID 41030439, 2025). "Our analysis aimed to explore the impact of a specific IL9 transfer on gene expression related to anti-inflammatory responses and autoimmunity in lung tissue." (PMID 38247549, 2024). "Interleukin 9 (IL-9)-producing helper T (Th9) cells have a crucial effector function in inducing allergic inflammation, autoimmunity, immunity to extracellular pathogens and anti-tumor immune responses." (PMID 31164892, 2019). "IL-9 is a critical cytokine in immunity to helminthic parasites, tumor immunity, and in inflammatory diseases including autoimmunity and allergic inflammation." (PMID 30442929, 2018). "Interleukin 9 (IL-9)-producing helper T (Th9) cells have a crucial function in allergic inflammation, autoimmunity, immunity to extracellular pathogens and anti-tumor immune responses." (PMID 28993609, 2017). "Likewise, in scenarios of autoimmunity, such as colitis, as well as in a mouse model of multiple sclerosis, IL-9 has also been demonstrated to play a proinflammatory role." (PMID 40962954, 2025). "IL-9 is capable of activating various cells, including Th17 and Treg lymphocytes, and therefore, depending on the local microenvironment, Th9 lymphocytes may direct the immune response towards autoimmunity/inflammation or tolerance." (PMID 29023386, 2017).
rheumatoid arthritis (26 papers, 2015 to 2025). A chronic, systemic autoimmune disorder characterized by inflammation in the synovial membranes and articular surfaces. "IL-9 has been reported to be elevated in the plasma of rheumatoid arthritis patients and is associated with increased osteoclastogenesis but its role in fracture healing has yet to be investigated." (PMID 38560342, 2024). "Remarkably, a separate study has delineated that a heightened prevalence of Th9 cells in the synovial tissue of rheumatoid arthritis (RA) patients is linked to disease activity, and that IL-9 can facilitate the Th17 differentiation." (PMID 38605942, 2024). "IL-9 secretion, which is closely related to Th9 cells associated with pro-inflammatory and degenerative processes in diseases such as rheumatoid arthritis, is significantly upregulated in the serum of OA patients." (PMID 35241691, 2022). "A study of psoriatic arthritis (PsA) and rheumatoid arthritis (RA), with OA as the control group, found that IL-9 promoted the growth and survival of locally activated T cells in an inflammatory environment." (PMID 39364408, 2024). "Interleukin (IL)-9 is an emerging player in the pathogenesis of various chronic inflammatory diseases including bone disorders like rheumatoid arthritis (RA) and psoriatic arthritis." (PMID 36732282, 2023). "A pro-resolution role of IL-9 has also been confirmed in patients with rheumatoid arthritis in clinical remission and in patients with lumbar radicular pain, where IL-9 was higher in patients with mild compared to severe disc herniations." (PMID 34224495, 2022). "Th9 lymphocytes and higher levels of IL-9 have been detected in patients treated for rheumatoid arthritis and in inactive periapical lesions, suggesting a potential role in tissue healing by modulating Th1-mediated osteoclastic activity." (PMID 33218047, 2020). "Supporting a role for IL-9+ ILC2 in resolution of inflammation in humans, rheumatoid arthritis patients in remission exhibited higher frequencies of IL-9+ ILC2 in both blood and synovial tissue as compared to patients with active inflammation." (PMID 29948108, 2018). "Targeting IL-26 may a potential therapeutic strategy for rheumatoid arthritis or other IL-9 plus IL-17 dominant diseases." (PMID 37108686, 2023). "In conclusion, our results support that IL-26 promotes IL-9- and IL-17-expressing macrophage and might initiate IL-9- and IL-17-related adaptive immunity in rheumatoid arthritis." (PMID 37108686, 2023). "Indeed, high serum levels of IL-9 and soluble IL-9R have been found in rheumatoid arthritis (RA) patients." (PMID 33995403, 2021). "IL-9-producing Th9 cells display a group of helper T cells with similarities to Th17 and Th2 T cells and have been shown to be involved in synovial inflammation in rheumatoid arthritis (RA) patients." (PMID 33995403, 2021). "Therefore, our purpose is to investigate whether IL-26 is involved in the regulation of IL-9 and IL-17 expression in rheumatoid arthritis." (PMID 37108686, 2023). "Previously, higher level of IL-9 was seen in rheumatoid arthritis (RA) and SLE patients than in the healthy group." (PMID 31697750, 2019). "In rheumatoid arthritis (RA), an increased expression of IL-9 and IL-9R is observed in synovial tissue, which also correlates with the degree of tissue inflammation." (PMID 31035677, 2019). "However, in the current study, the mechanism leading to the different driven Th17 cells count in alveolar space might differ from that in rheumatoid arthritis for the similar concentrations of CCL20 in BALF from both IL-9−/− and WT PCP mice." (PMID 29887863, 2018). "IL-9 has been shown to promote osteoclastogenesis in individuals with rheumatoid arthritis (RA)." (PMID 41368642, 2025). "In recent years, IL-9, a member of γc family, has been observed to be involved in the pathogenesis of various chronic inflammatory bone disorders like rheumatoid arthritis (RA), psoriatic arthritis, etc." (PMID 36732282, 2023).